IL1A (interleukin 1 alpha)
Diseases named in the same sentence as IL1A in open-access papers (continued):
Sharing a sentence is not in itself a finding about the gene and the disease.
cardiovascular disease (25 papers, 2012 to 2026). "Interestingly, IL-1α and IL-1β are both known to be critical paracrine (and endocrine) mediators of inflammation linked to lung and cardiovascular disease." (PMID 32316988, 2020). "Among variants present in the propositus (III2), the KNG1 Ile197Met has been associated to decreased kininogen and factor XI levels, and the homozygous IL1A Ala114Ser to ~50% decreased IL-1α release, and in turn with cardiovascular disease." (PMID 37762110, 2023). "Rilonacept, a decoy receptor that binds IL-1β and IL-1α, also displayed potential therapeutic effects in cardiovascular diseases, but there was only one clinical trial on cardiovascular diseases, and the subjects were patients with recurrent pericarditis." (PMID 36111168, 2022). "The first two members of the IL-1 family—IL-1α and IL-1β—have been extensively studied in cardiovascular disease." (PMID 34884857, 2021). "A study suggests that the role of IL-1α in atherogenesis should be targeted in patients with cardiovascular disease." (PMID 30479572, 2018). "Each of the other three interactive cytokines (IL-1α, sCD40L, and IP-10) is also involved in experimental and/or clinical cardiovascular disease." (PMID 24013901, 2013). "While monoclonal antibodies targeting IL-1α and IL-1β have transformed the management of autoinflammatory, rheumatologic, and cardiovascular disease, their efficacy is often limited by poor tissue penetration, compensatory cytokine networks, and systemic immunosuppression risks." (PMID 42006724, 2026). "The IL-1 family of ligands and receptors are associated with both acute and chronic inflammation, and IL-1α is an intracellular cytokine involved in various immune responses and inflammatory processes, that is known to be upregulated in cardiovascular diseases." (PMID 31507404, 2019). "IL-1α, IL-12p70, and CCL5 are pro-inflammatory cytokines/chemokines that may contribute to the inflammatory pathways and the accompanying brain dysfunctions as well as peripheral inflammation-linked disorders, including cardiovascular diseases, which frequently occur in persons who use MA." (PMID 37996407, 2023). "Studies have shown that main neuroactive cytokines involved in hypothalamic inflammatory mechanisms related to cardiovascular diseases are TNF-α, IL-6, IL1-α/IL-1β, and IL-10." (PMID 33967677, 2021). "In addition to modifying IL-1α, IL-1β, IL-6, TNF-α, and IL-17A levels, five nights of sleep restriction are accompanied by increased heart rate; both proinflammatory cytokines and hypertension are important risk factors for development of cardiovascular disease." (PMID 24367384, 2013).
neurodegenerative disease (19 papers, 2018 to 2025). A disorder of the central nervous system characterized by gradual and progressive loss of neural tissue and neurologic function. "The C allele of the IL-1α rs1304037 variant was reported to be associated with increased severity of IVD degenerative disease and the accompanying modic changes." (PMID 39287911, 2024). "The IL-1α gene in particular is linked to an increased risk of IVD degenerative disease." (PMID 39287911, 2024). "Decreased expression of pro-inflammatory genes, which are associated with neurodegenerative disease or astrocyte and microglia phenotypes Cd40, C1qB, Cd68, Cd45, Aqp-4, Il1α, Fkbp5, Ggta1, Cd16, H2-T23, and Serping1, was observed following C-32:6 treatment and C1qC, Tspo, and Gbp2 with FFA C-34:6." (PMID 37740008, 2023). "A sub-state of reactive astrocytes induced by proinflammatory factors TNF, IL-1α, and C1q (“TIC”) has been implicated in many neurodegenerative diseases as a source of neurotoxicity." (PMID 35592112, 2022). "It is interesting to highlight that just NLRP3 expression remains at 24 h, and these data were confirmed by IL-1α secretion, validating the timepoints that interplay between these phenomena and supporting the role of inflammasome in neurodegenerative diseases." (PMID 33946176, 2021). "The IL-1 family consists of eleven isoforms, out of which IL-1α and IL-1β play a strong pro-inflammatory role in neurodegenerative diseases." (PMID 34691061, 2021). "The relevance of microglial activation of neurotoxic astrocytes in neurodegenerative disease was substantiated whereby genetic deletion of Il1a, Tnf and C1qa produced strong neuroprotective and disease-modifying outcomes in a SOD1G93A mouse model of ALS, including a 54% extension to survival." (PMID 38317225, 2024). "Hypersensitivity to IL-1α in IVD cells has been described as a significant motivator for degeneration, playing a key role in extracellular matrix metabolism and modic changes—an MRI trait associated with IVD degenerative disease." (PMID 39287911, 2024). "Conversely, astrocytes are abnormally activated by inflammatory cytokines, such as interleukin-1α (IL-1α) and TNF-α, which are released from activated microglia in neurodegenerative diseases that include Alzheimer’s disease and multiple sclerosis." (PMID 41192481, 2025). "We investigated the effects of SM on IL-1α/TNF-α-induced astrocyte activation, which mimics astrocyte phenotypes in neurodegenerative disease conditions, using HASTR/ci35 cells, a human astrocyte-like cells." (PMID 41192481, 2025). "Due to its anti-inflammatory effect, some studies have shown that QUR can be useful as a complementary treatment for neurodegenerative diseases such as AD or PD, by stimulating the expression of HO-1, which reduces NO production and suppress pro-inflammatory markers, TNF-α and IL-1α." (PMID 34220504, 2021). "While EVs from both 14 and 21 DIV cultures reduced slightly the secretion of the cytokines IFNγ and IL-1a, only EVs from 14 DIV cultures decreased the levels of IL-6, a cytokine predominantly released in neurodegenerative diseases through EVs in the CNS and involved in astrogliosis." (PMID 35163295, 2022).
adenocarcinoma (9 papers, 2008 to 2025). A common cancer characterized by the presence of malignant glandular cells. "We found that the expression of A3A, A3B, and IL1A was modestly elevated (1.4–1.7-fold) in squamous cancers as compared with adenocarcinomas." (PMID 40323013, 2025). "Prognostic analysis using the Kaplan–Meier Plotter revealed that higher expression of CSF3 and CCRL2, as well as lower expression of IL1A, were significantly associated with prolonged PPS in adenocarcinoma patients undergoing chemotherapy." (PMID 39727962, 2024). "We used a well-established HeLa (adenocarcinoma) cell line as a model system to investigate the regulation of IL-1α expression by SP in neoplastic cervical epithelium." (PMID 25237386, 2014). "In addition, IL-1α immunostaining was observed in endothelial cells lining the vasculature in all adenocarcinoma tissue sections investigated." (PMID 25237386, 2014). "Hence, using HeLa (adenocarcinoma) cells, normal and neoplastic cervical tissue explants this study investigated the role of SP in the regulation of IL-1α expression in the cervix and transduction pathways by which SP induces the expression of IL-1α in neoplastic and normal cervical epithelium." (PMID 25237386, 2014). "We found previously that IL-1α/β are present in human and experimental MPE and that MPE-competent adenocarcinomas trigger myeloid cells to secrete IL-1β35." (PMID 29445180, 2018). "Employing HeLa (adenocarcinoma) cell line as a model system we identified PGE2 and EGF as possible ligands responsible for SP-mediated induction of IL-1α in these neoplastic cells." (PMID 25237386, 2014). "Consistent with this, the expression of A3A – and to a lesser extent A3B, IL1A, and IL1B – was correlated with the squamous markers but not the adenocarcinoma markers in this dataset." (PMID 40323013, 2025).
infectious disease (8 papers, 2013 to 2024). A disorder directly resulting from the presence and activity of a microbial, viral, or parasitic agent in humans. "Increased levels of inflammatory cytokines, primarily IL-1α and IL-6, may be associated with periodontal, oncological, and infectious diseases." (PMID 39338495, 2024). "Its levels are elevated in many inflammatory and infectious diseases including TB, and serum levels decline with treatment; its main role is the competitive inhibition of the inflammatory effects of IL-1α and IL-1β." (PMID 23691173, 2013).
renal disease (7 papers, 2016 to 2023). "In the present study, IL-1α and IL-1β were higher expressed in surviving dogs with all types of renal diseases compared to healthy dogs." (PMID 26824356, 2016). "In addition, levels of IL-1α, IL-1β TNFα, INFγ, IL-2 and IL-10 were elevated in the sera of CKD compared to sham, suggesting that the chronic state of renal disease affects the inflammatory network." (PMID 29889834, 2018). "Dogs from all groups of renal diseases showed elevated expression of IL-1α, IL-1β, IL-10, TGF-β and iNOS, a pattern that may therefore be considered the signature for canine renal disease." (PMID 26824356, 2016).
cardiac disease (5 papers, 2018 to 2023). "IL-1α and IL-1β are proinflammatory cytokines and their levels are correlated with the severity and pathogenesis of heart disease." (PMID 37047468, 2023). "As proinflammatory/profibrotic mediators are also augmented in cardiac disease, the effect of a range of proteins, including Ang II, TGFβ1, IL-1β, IL-1α, TNFα, IL-6 and IL-6 in combination with the sIL-6R on Cx43 mRNA expression was examined in CFs." (PMID 31909243, 2020). "IL-1 comprises 2 distinct gene products (IL-1α and IL-1β) that have generally indistinguishable biological activities and play a significant role in the pathogenesis of heart disease." (PMID 31393855, 2019).
immune disorders (5 papers, 2020 to 2024). "The cited study revealed inflammation of the small intestine in pregnant sows as well as changes in newborn piglets where immune dysfunctions and increased expression of the genes encoding proinflammatory cytokines IL-6, IL-1α, IL-1β, and TNFα were observed in the small intestine." (PMID 32471145, 2020). "B cells in RA synovium induce the production of cytokines such as IL-1α, IL-23, IL-12, IL-6, and TNF-α, causing bone damage, inflammation, and immune disorders." (PMID 39139563, 2024). "Local synthesizing process for cytokine (e.g., IL-1α, IL-23, IL-12, IL-6, and TNF-α) under the induction from local autoreactive B cell was suggested to impact pathology-associated RA cells, triggering bone injury, inflammation, and immune disorder." (PMID 34691030, 2021). "The increases in the proinflammatory cytokines IL-1a, IL-8, IL-17A, IL-12p40, TNF-β, MCP-1, IL-2, and IL-12p70 and the anti-inflammatory cytokines IL-10 and IL-13 observed in AD patients in our study are consistent with prior evidence of immune dysfunction in AD." (PMID 39346576, 2024).
neurological disease (4 papers, 2019 to 2023). "During CM Plasmodium parasites sequestered in the CNS within erythrocytes cause the production of proinflammatory cytokines, such as TNF-α, LTα, IFN-γ, IL-1α, and IL-1β, which contribute to the hyperinflammatory state of this neurological disorder." (PMID 35222377, 2022). "Recent studies indicated that activated microglia can convert astrocytes into the neurotoxic A1 phenotype via the secretion of IL‐1α, TNF‐α, and C1q, and dysfunction of astrocytes critically impacts neuronal survival in various neurological diseases." (PMID 37830170, 2023). "In neurological disease research, WBI has been replaced by HIR as the gold standard, overcoming many of the WBI side-effects that include a sustained pro-inflammatory environment expressing IL-1α and perturbation of the BBB." (PMID 30722781, 2019).
metabolic disorders (3 papers, 2020 to 2025). "Therefore, inhibition of IL-1a has a therapeutic potential for the prevention and/or treatment of metabolic disorders in elderly population." (PMID 31980643, 2020).
head and neck tumors (1 paper, 2024). "In addition, IL-1A can regulate the function and activity of immune cells, affecting the immune response of head and neck tumors." (PMID 39461030, 2024). "The role of IL-1A in the occurrence and development of head and neck tumors is complex." (PMID 39461030, 2024). "In this study, it was found that IL-1α, IL-1β, IL1R1, IL1RL1, IL1F10, IL33, CASP1, and AIM2 were highly expressed in head and neck tumors, while IL1RN, IL1RAPL1, IL1RAPL2, IL18BP, IL18R1, and IL18RAP were low in expressed, which is consistent with previous literature." (PMID 39461030, 2024).
IL1A also shares sentences with these, for which no sentence is quoted: idiopathic pulmonary fibrosis (7 papers); Anxiety (6); neuroblastoma (5); AIDS (4); cerebral artery (4); multiple myeloma (4); necrotizing enterocolitis (4); renal cell carcinoma (4); acute myocardial infarction (3); chronic rhinosinusitis (3); corneal ulcer (3); dental caries (3); helminth infection (3); mesothelioma (3); pemphigus vulgaris (3); primary open angle glaucoma (3); renal fibrosis (3); Thrombocytopenia (3); acute myeloid leukemia (2); alopecia (2); Arrhythmia (2); B-cell lymphoma (2); cerebral malaria (2); dermatomyositis (2); diabetic foot ulcer (2); eating disorder (2); gestational diabetes (2); hematological disease (2); Hydrocephalus (2); hyperlipidemia (2).
A further 140 diseases each share a sentence with IL1A in 2 papers or fewer.